TPM4 (tropomyosin 4)
Diseases named in the same sentence as TPM4 in open-access papers (continued):
Sharing a sentence is not in itself a finding about the gene and the disease.
cancer (27 papers, 2011 to 2025). A tumor composed of atypical neoplastic, often pleomorphic cells that invade other tissues. "The findings of the comprehensive pan-cancer analysis revealed that TPM4 has a certain diagnostic and prognosis value in most cancers." (PMID 36993958, 2023). "We explored the expression pattern of TPM4 to determine its pan-cancer diagnostic and prognostic value, genetic changes, and epigenetic status." (PMID 36993958, 2023). "TPM4 serves as a promising biomarker for prognostic and diagnostic and immunotherapy in cancers, including GC." (PMID 36993958, 2023). "Collectively, TPM4 expression has diagnostic and prognostic value in different cancers, including STAD." (PMID 36993958, 2023). "The EPIC online tool showed that eight cancer-associated immune cells were related to TPM4 expression in different cancers, especially in KIPR, LUAD, PCPG, PRAG, STAD, and UVM." (PMID 36993958, 2023). "Additionally, we examined the relationship among the expression of TPM4, immune infiltration by pan-cancer cells, and the TPM4-associated antitumor drug response." (PMID 36993958, 2023). "Therefore, TPM4 could be used as a potential diagnostic marker for detecting mutations and pan-cancer epigenetic changes." (PMID 36993958, 2023). "Since DNA methylation of the CpG islands within the gene promoter region can cause the silencing of gene expression, we assessed the promoter DNA methylation levels of TPM4 in 19 types of cancers and normal tissues." (PMID 36993958, 2023). "In our study, TPM4 expression was upregulated in most cancer tissues compared to that in normal paired tissues." (PMID 36993958, 2023). "Our study is the first to reveal the potential applications of TPM4 as a predictive target for diagnosis, prognosis, as well as anti-cancer therapy within GC." (PMID 36993958, 2023). "TPM4 expression was positively related to most m1A, m5C, and m6A methylations in pan-cancer tissues." (PMID 36993958, 2023). "We assessed the promoter DNA methylation levels in TPM4 in normal tissues and 19 types of cancer tissues." (PMID 36993958, 2023). "These outcomes indicate that TPM4 is a prospective biomarker of diagnosis and prognosis in different cancers, including GC." (PMID 36993958, 2023). "TPM4 is a prospective marker for the diagnosis, treatment outcome, immunology, chemotherapy, and small molecular drugs targeted for pan-cancer treatment, including GC treatment." (PMID 36993958, 2023). "We used UCSC Xena, The Cancer Genome Atlas (TCGA), Genotype-Tissue Expression Project (GTEx), TIMER2.0, GEPIA, cBioPortal, Xiantao tool, and UALCAN websites and databases for the extraction of pan-cancer data on TPM4." (PMID 36993958, 2023). "TPM4 expression was altered in 131 samples collected from 2565 patients with different cancer types, which accounted for 5% of the samples." (PMID 36993958, 2023). "Previous research reported that TPM4 is related to the occurrence and metastasis of several cancers." (PMID 34850589, 2022). "We propose a dual role for miR-133a in muscle growth and differentiation as well as in cancer development and progression, in which TPM4 has a central role." (PMID 34575979, 2021). "TPM4 is involved in the regulation of actin binding proteins, and TPM4 was reported that it related the progress in several cancers." (PMID 33390785, 2021). "The data with respect to the expression of the TAp63 isoform in CRC tissue leads to consider the axis miR-133a-TPM4 as the major effector in cancer." (PMID 34575979, 2021). "Tropomyosin-4 is abnormally expressed in different tumors and plays different roles in promoting or suppressing cancer." (PMID 34234838, 2021). "Recent evidence correlated TPM4 expression with cancer development, specifically with neoplastic cell invasion and metastatisation." (PMID 34575979, 2021).
cancer (continued). "Remarkably, USP22 knockout had pronounced effects on expression of these important cancer-associated gene sets such as c-Myc, E2F, and selected genes including ALDH1A3, CCNE1/G1, E2F6, HOXA1, MMP9, NFKB2, TP63, TPM4, SET7/9 were validated by qRT–PCR." (PMID 31842906, 2019). "Tropomyosin 4 expression in the cytoplasm of dysplastic and cancer cells gradually decreased from SCE to InvSCC, with a significant difference between CIN3 and InvSCC." (PMID 21119665, 2011). "We investigated the pan-cancer genetic alterations in TPM4 across the cBioPortal." (PMID 36993958, 2023). "Collectively, TPM4 may affect antitumor immunity through its association with immune infiltrating cells, ICPS, MSI, TMB, and NEO in pan-cancer tissues." (PMID 36993958, 2023). "TPM4 expression correlated with TILs in different cancer types." (PMID 36639743, 2023). "A comprehensive analysis of the pan-cancer function of TPM4 is necessary." (PMID 36993958, 2023). "Therefore, elevated levels of inflammatory cytokines, which are associated with increased risk of both cardiovascular disease and cancer, appear to cause marked decreases in expression of HMW isoforms from TPM1 and TPM4." (PMID 27649540, 2016). "Therefore, TPM4 may be a prospective biomarker for the immunotherapeutic response in patients at a pan-cancer level, including STAD." (PMID 36993958, 2023). "Therefore, TPM4 is likely to be used as a marker for several cancers." (PMID 33390785, 2021). "Tropomyosin 4 (TPM4), a member of the tropomyosin family, is aberrantly expressed and plays an important role in a variety of cancers." (PMID 36639743, 2023). "TPM4 is hypomethylated in different cancers, including STAD, and 25 CpG sites of TPM4 were observed in STAD." (PMID 36993958, 2023). "TPM4 was among the most upregulated genes in ESCC and various cancers at the protein level.37–40 In the GSE149609 cohort, we confirmed the upregulation of TPM4 in ESCC patients." (PMID 35418165, 2022). "Previous studies have identified the key role of TPM1–4 in some cancers, especially the role of TPM3 and TPM4 in HCC development." (PMID 34850589, 2022). "To date, several more ALK hybrid proteins have been identified in various cancer types, such as TRK-fused gene (TFG)-ALK, tropomyosin 3 (TPM3)-ALK, tropomyosin 4 (TPM4)-ALK, clathrin heavy chain-like 1 (CLTCL1)-ALK, and moesin (MSN)-ALK." (PMID 23667670, 2013). "TPM4 expression has been observed in non-muscle cells, such as fibroblasts, endothelial cells, and certain types of cancer cells." (PMID 38732116, 2024). "Furthermore, our study showed that in most cancers, including STAD, the expression of TPM4 mRNA exhibited positive correlation with a majority of m1A, m5C, and m6A methylation regulators." (PMID 36993958, 2023). "Studies have shown that enhanced TPM4 could promote the migration of certain types of cancer cells without participating in cell proliferation and EMT progression." (PMID 37328795, 2023). "However, an integrated bioinformatics analysis of the function of TPM4 in pan-cancer tissues across multiple databases has not been performed to date." (PMID 36993958, 2023). "Taken together, the results suggest that crizotinib is effective for treating ALK-driven cancer and might be a new therapeutic drug, without cardiac or respiratory muscle toxic effects, for TPM4-expressing cancers." (PMID 31278140, 2019). "Moreover, we also intend in an upcoming study to evaluate alterations in the salivary TPM4 expression in patients undergoing versus those not undergoing different cancer treatments, including chemotherapy and/or radiation." (PMID 31804537, 2019). "Our analysis suggests that whereas gene level expression estimates of TPM4 and MITF contribute little to the discrimination of cancer cell lines from non-oncogenic cells, expression estimates specific to one or more isoforms of these genes have a better discriminating power." (PMID 23594586, 2013).
TPM4 also shares sentences with these, for which no sentence is quoted: anaplastic large cell lymphoma (2 papers); breast invasive carcinoma (2); Cirrhosis (2); oral squamous cell carcinoma (2); acute myeloid leukemia (1); acute myocardial infarction (1); alcoholic cirrhosis (1); Amoebiasis (1); arthrogryposis (1); astrocytoma (1); atrial fibrillation (1); autoimmune disease (1); autosomal dominant macrothrombocytopenia (1); bacterial infection (1); brain disorder (1); cardiac hypertrophy (1); cardiovascular disease (1); Cerebral ischemia (1); cervix (1); clear cell sarcoma of the kidney (1); dermatitis (1); dermatofibrosarcoma protuberans (1); diffuse large B-cell lymphoma (1); emphysema (1); endometrial stromal sarcoma (1); escherichia coli infection (1); esophageal carcinoma (1); granulocytic sarcoma (1); head and neck squamous cell carcinoma (1); heart diseases (1).
A further 25 diseases each share a sentence with TPM4 in 1 paper.